MTOR (mechanistic target of rapamycin kinase)
Diseases named in the same sentence as MTOR in open-access papers (continued):
Sharing a sentence is not in itself a finding about the gene and the disease.
cancer (continued). "The PI3K/Akt/mTOR pathway is involved in several cell processes, including proliferation, metabolism and motility, therefore it is not surprising that its dysregulation corresponds to uncontrolled proliferation and propagation in a wide spectrum of cancers." (PMID 32355893, 2019). "Therefore, targeting ALDH3A1 and mitochondrial complex I using gossypol and phenformin results in almost complete depletion of ATP, which downregulates cancer cell growth through mTOR inhibition and further induces cell death by disturbing homeostasis." (PMID 31705020, 2019). "Cancer genomes with lower 45S rDNA copies show evidence of mTOR hyperactivity." (PMID 31338556, 2019). "Moreover, the C‐dots disrupt DNA repair through BER pathway and inhibits cancer cell proliferation likely through mTOR, Pim‐1, EGFR, and DNA damage pathways." (PMID 31692950, 2019). "The activated Akt-mTOR delays the death of cancer cells and promotes their proliferation." (PMID 30874538, 2019). "Growing evidence has demonstrated the critical role of PI3K/mTOR pathway in the maintenance of CSCs, and that targeting PI3K/mTOR signaling may be beneficial in cancer treatment by eliminating CSCs." (PMID 30635656, 2019). "In an experimental model of cancer cachexia, a 3% leucine-rich diet showed positive effects on protein synthesis in skeletal muscle, leading activation of the mTOR pathway and reduction of protein degradation by inhibiting the ubiquitin-proteasome pathway in Walker-256 tumour-bearing rats." (PMID 31200474, 2019). "Finally, combined PI3Kα and mTOR targeting disrupted cancer stem cell frequencies in vitro and significantly inhibited tumour growth in a flank tumour xenograft mouse model in vivo." (PMID 31492956, 2019). "Furthermore, the mTOR signalling stimulates fatty acid synthesis in cancer, via the persistent activation of sterol regulatory element-binding protein-1c (SREBP1c)." (PMID 30970654, 2019). "It has been shown that RES could inactivate the PI3K/AKT/mTOR pathway and thus decrease the growth of various cancer cells in a dose-dependent manner." (PMID 31159437, 2019). "Some of the transcription factors that were specifically expressed in OS-DW cells were ATF6, CDX2, FOSL1, PRDX3, FZD6, MYNN, TRAF1 which are known to regulate pathways implicated in cancers like, Wnt/Hedgehog/Notch signaling, MAPK signaling, Apoptosis and mTOR signaling." (PMID 31690262, 2019). "Therefore, although preliminary studies showed promising efficacy of dual mTOR inhibitors in various of cancers, the clinical significance should still be investigated in clinical trials to prove their activities in cancer treatment." (PMID 30682771, 2019). "The PI3K/AKT/mTOR signaling pathway is crucial for maintaining control of proliferation in mammalian cells, where uncontrolled activation results in unstoppable proliferation of tumor cells in cancers." (PMID 31281796, 2019). "However, a recent study has shown that compound C, a commonly used inhibitor of AMPK, induces autophagy by blocking the Akt/mTOR pathway in a number of cancer cell lines." (PMID 31366950, 2019). "Cancer cells often use mTOR as a mechanism to increase their capacity to grow." (PMID 31030467, 2019). "Therefore, both HPV-positive and HPV-negative HNSCC cells are characterised by deregulated mTOR signalling, which impairs their metabolism and thus sustains the survival and growth of cancer cells in a vicious cycle." (PMID 30970654, 2019). "It is conceivable that inhibiting the utilization of scavenged protein, for example, by blocking the cytosolic export of amino acids that require PIKfyve activity, could enhance the anti-cancer effects of mTOR inhibition." (PMID 30967004, 2019).
cancer (continued). "Down-regulation of AKT/PI3K leads to inactivated mTOR and induce autophagy in cancer cells." (PMID 30096805, 2018). "Moreover, mLST8 knock down induces dissociation of mTORC1/2 complexes in cancer cells and significantly suppresses both mTOR complexes formation, thereby leading to a new role of mLST8 even in mTORC1." (PMID 29351204, 2018). "In response to proliferating signal in cancer cells, mTOR activates ATF4, which stimulates the expressions of MTHFD2 and other enzymes for serine synthesis and THF cycle, providing amino acid substrates and one-carbon units required for the de novo purine synthesis." (PMID 30105018, 2018). "PI3K/Akt/mTOR pathway is known to control the progression of cancer." (PMID 29970122, 2018). "Inhibitors of mTOR have been widely studied in cancer therapy, as they may sensitize cancer cells to radiation therapy." (PMID 29518028, 2018). "The PI3K/AKT/mTOR pathway is one of the comprehensive signaling pathways that regulate cell proliferation, growth, metabolism, and cell survival and is one of the most periodically deregulated pathways in cancer." (PMID 30096805, 2018). "The PI3K/AKT/mTOR pathway is a well established driver of cancer in humans." (PMID 29357975, 2018). "Previous studies demonstrated that PI3K/AKT/mTOR signaling pathway is one of the most frequently altered pathways in human cancer and dysregulation of this pathway contributes to cancer initiation and progression, including breast cancer, lung cancer, and renal carcinoma." (PMID 30723697, 2018). "Cancer cells often exploit mTOR as a mechanism to enhance their capacity to grow." (PMID 29848950, 2018). "Notably, pathways of the RNA degradation, mTOR signaling pathway, immune system and pathways in human diseases, especially cancer were significantly enriched by target genes." (PMID 30593264, 2018). "In addition, other studies have demonstrated that Ki-67, as well as mTOR, was expressed at significantly higher levels in invasive cases than carcinoma in situ cases." (PMID 29503810, 2018). "Similarly, the PI3K pathway independent of AKT has also been demonstrated to promote different cancers via mTOR, PDK1 and cMyc." (PMID 29401696, 2018). "mTOR play a critical role in cancer cell growth and is a promising target for cancer therapy." (PMID 30356017, 2018). "Hyperactivation of the PI3K-Akt-mTOR signaling is a common alteration in cancer." (PMID 29707520, 2018). "It was reported that mTOR can regulate NF-κB activity in cancer cells, therefore, we sought to determine whether IL-23-induced mTOR is the upstream signaling to regulate NF-κB activation in TFCs." (PMID 29434604, 2018). "Since both in vitro and in vivo studies showed that mTORC2 plays a pivotal role in cancer growth and survival, targeting mTOR with TORKIs might be more efficacious than rapalogs because of AKT phosphorylation inhibition downstream of mTORC2." (PMID 29692710, 2018). "In addition, exposure of cancer cells to pterostilbene resulted in a decrease in the phosphorylated (activated) form of mTOR (Ser2448)." (PMID 30619763, 2018). "However, mTOR activity is frequently deregulated in cancer, where it plays a key oncogenetic role driving tumor cell proliferation, survival, metabolic transformation, and metastatic potential." (PMID 29949919, 2018). "This suggests that mTOR might be involved in tumour-related cachexia and, conversely, that mTOR inhibitors during cancer treatments might contribute to tumour cachexia." (PMID 30061533, 2018). "The mammalian target of rapamycin (mTOR) is a downstream target of AMPK involved in regulating energy homeostasis by modulating cellular processes, such as protein synthesis and autophagy implicated in cell proliferation and tumorigenesis in cancer." (PMID 29915588, 2018).
cancer (continued). "The most common individual cancer drugs causing DIILD were identified as bleomycin, gemcitabine, epidermal growth factor receptor (EGFR)-directed therapies, mechanistic target of rapamycin protein (MTOR) inhibitors and immune checkpoint inhibitors." (PMID 30326612, 2018). "Given the success of mTOR and anti-estrogen therapy in ER-positive breast cancer, this combination may be useful in other cancer types that are dependent on hormonal or PI3K/mTOR signaling." (PMID 30053901, 2018). "Rapamycin, also known as Sirolimus, is a macrolide and an inhibitor of the PI3K/Akt/mTOR pathway, a pathway that is often deregulated in cancer, which in turn has given Rapamycin potent anti-cancerous properties in a variety of solid tumors and blood-related malignancies." (PMID 30323898, 2018). "In the mTOR users, 90 patients were diagnosed with cancer (12.13%)." (PMID 30117312, 2018). "The key role of mTOR in cell growth and energetics and inhibition of autophagy suggests how the pathological activation of this pathway is bound to cell survival, proliferation and cancer development." (PMID 29509701, 2018). "Neither high- nor low-dose exposure to mTOR inhibitors was associated with increased risk of cancer or mortality." (PMID 30473931, 2018). "Through activating UPR, ATF6 may play an important role in promoting survival of dormant cancer cells via stimulating the mTOR pathway." (PMID 28884228, 2018). "The role of mTOR in protein synthesis makes it indispensable for the survival of cancer cells." (PMID 29844464, 2018). "Additionally, in a study on laryngeal SCC, a cancer which is strongly correlated with tobacco exposure, mTOR and EGFR pathways were highly overexpressed." (PMID 30308005, 2018). "A major issue is that most cancers develop resistance against monotherapy with mTOR inhibitors." (PMID 28616837, 2018). "Many cancers rely on constitutive mTOR activity to maintain cellular growth and proliferation." (PMID 29211698, 2018). "Previous studies reported that isothiocyanates can suppress mTOR in cancer cells." (PMID 29300316, 2018). "In cancer cells, HIF-1 can also be activated by loss of function of the tumor suppressor VHL and by gain of function of oncogenes leading to the activation of the PI3K/AKT/mTOR pathway." (PMID 30510924, 2018). "Abnormal over-activation of mTOR was observed in many cancer models including NETs, and inhibition of mTOR by rapamycin and its analogues such as RAD001, known as everolimus (Afinitor, Novartis Oncology), was shown to arrest tumor cell proliferation and to slow the tumor growth." (PMID 30009041, 2018). "In addition, metabolic dysfunctions, such as hyperglycemia is a common side effect in cancer patients treated with mTOR inhibitors, including everolimus." (PMID 29441052, 2018). "Moreover, mTOR regulates the synthesis of proteins that are responsible for the growth and survival of cancer cells." (PMID 30275391, 2018). "However, several reports in cancer biology strongly suggest an active role for miR-21 in regulating mTOR signaling largely through PTEN/PI3K/AKT pathway." (PMID 30305865, 2018). "Thus, the function of the mTOR pathway in cancer development makes it interesting for targeted therapy in different tumors." (PMID 29932116, 2018). "Accordingly, emerging evidence suggests that mTOR and mTOR inhibitors influence cancer cachexia." (PMID 30061533, 2018). "The conversion from CNIs to mTOR inhibitors induces protection against cancer." (PMID 30473931, 2018). "Targeting mTOR is emerging as an important approach in cancer therapeutics." (PMID 30250638, 2018). "Because SEMA3F suppresses rapamycin-induced Akt activation, the combination of SEMA3F with mTOR inhibitors may provide a clinical benefit in cancer therapy." (PMID 30532711, 2018).
cancer (continued). "The mammalian target of rapamycin (mTOR) pathway is commonly activated in human cancers." (PMID 29423269, 2018). "Rapamycin is the first mTOR inhibitor that has been used in anti-cancer therapy." (PMID 29932116, 2018). "As highlighted above, mTOR plays a central role in coordinating the environmental stimuli and cell metabolic responses, also because of its function in immune cell homeostasis and activation, and thus represents a potential target for cancer immunotherapy." (PMID 30126252, 2018). "mTOR inhibitors have been used in clinical treatments of several human cancers." (PMID 30285764, 2018). "In addition, mTOR pathway was downregulated following the treatment with rfhSP-D, which is crucial for cell survival and proliferation, and thus, to protect the cancer cells from apoptosis." (PMID 29915574, 2018). "Notably, activated AMPK pathway impedes mTOR signaling, and shuts down glycolytic gene expression leading to antiproliferative effects in cancer." (PMID 29527212, 2018). "This study explored the effects of COE on the proliferation and apoptosis in the HepG2/mTOR+ cells, which may bring new hope for clinical treatment of cancer characterized with mTOR activation." (PMID 30526568, 2018). "Furthermore, a variety of activating mutations in MTOR are well-known in both RCC and other cancer types, and in some cases are associated with exceptional response to rapalog therapy." (PMID 30256787, 2018). "Targeting mTOR signaling has therefore become an attractive strategy in cancer therapy." (PMID 29351204, 2018). "Indeed, adressing the intricated regulation of redox metabolism, tumour proteostasis and mTOR signaling, together with the complex regulatory loops and functional redundancies that characterize mTOR signaling in cancer cells promises to be challenging." (PMID 29492203, 2018). "PI3K is known to play a key role in Akt–mTOR signaling and help cancer cells to survive." (PMID 29434218, 2018). "The effect of mTOR inhibition on tumour cachexia in cancer patients remains poorly investigated." (PMID 30061533, 2018). "This suggests a broad-spectrum cytostatic activity for FAF/Rapa against mTOR driven cancers." (PMID 30386244, 2018). "Taken together, these findings suggest that STK25 could serve as a potential target in the treatment of cancers that correlate with dysregulated glycolysis that is induced by activation of mTOR signaling." (PMID 29996891, 2018). "While the mTOR pathway plays several roles in cancer cell biology, including resistance to apoptosis and metabolic reprogramming, this association with ALDH expression and the emerging evidence of a functional role for ALDH highlights a potential new target for overcoming chemoresistance." (PMID 30410720, 2018). "According to their role in cancer cell metabolism, mTOR and LDH-A could be expected to be functionally related." (PMID 30138330, 2018). "PEC shows the down regulation of PI3K/AKT/mTOR pathway which is a major regulator of autophagic and apoptotic cell death in cancer cells that leads to the down-regulation of p-4EBP1, p-p70S6K, and p-eIF4E in PEC treated cells when compared with the untreated cells." (PMID 30096805, 2018). "Given that 10 ng/mL TGF-β1 can activate both the TGF-β/Smad and PI3K/Akt/mTOR pathways to promote EMT in cancer cells, we hypothesized that deactivating these two signaling pathways may reverse EMT in TGF-β-treated HCC cells." (PMID 29882900, 2018). "As the PI3K/Akt/mTOR signalling pathway plays a very important role in cancer therapeutic resistance including CaP, we investigated whether this pathway is involved in the effects of EpCAM-KD on CaP xenografts using IHC." (PMID 30419852, 2018).
cancer (continued). "An attractive metabolic target is mTOR, which is activated both in cancer and immune cells." (PMID 30123774, 2018). "In addition, the activated NF-κB provides a positive feedback to regulate EGFR/Akt/mTOR pathway, thereby promoting the cell proliferation in cancers such as HNSCC." (PMID 29381751, 2018). "How the interaction with and the inhibition by mTOR might affect possible roles of TPCs in cancer development and progression remains to be elucidated." (PMID 29303993, 2018). "The specific role of Treg in different types of cancer may differ and therefore, the effect of mTOR inhibitors on different cancer types may differ too." (PMID 30473931, 2018). "Manipulations of Ubtor function may potentially be utilized to optimize mTOR signaling activities for treatments of cancers and other diseases." (PMID 30080879, 2018). "Rapamycins are immunosuppressant and anti-cancer drugs that inhibit the kinase mTOR." (PMID 30271915, 2018). "mTOR inhibitors dose exposure did not change the risk of cancer development, or all-cause mortality when compared to that in non-users group." (PMID 30473931, 2018). "The efficacy of mTOR inhibition in the treatment of various types of cancer is still being evaluated, and there are many possibilities that have yet to be explored in identifying areas where rapamycin might prove to be an effective treatment for cancer." (PMID 30110936, 2018). "Indeed, two Food and Drug Adminstration (FDA)-approved mTOR inhibitors, temsirolimus and everolimus, showed improved clinical outcomes and provided additional options for difficult-to-treat cancers." (PMID 29562667, 2018). "Therefore, we suggest that PGAM1 is a downstream effector of mTOR signaling and a potential target for cancer treatment." (PMID 29362480, 2018). "Moreover, recent studies demonstrated that leucine supplementation improves muscle protein synthesis in the elderly and in cancer patients by stimulating the mammalian target of rapamycin (mTOR) pathway." (PMID 29670613, 2018). "However, higher concentrations of asTORi ultimately reduced HSV1-dICP0 infection in certain cancer cell lines, suggesting that excessive mTOR suppression can limit HSV1-dICP0 protein synthesis and concomitant infection." (PMID 30138450, 2018). "Nevertheless, as we found that impact of PTX and ABT-737 on these pro-apoptotic proteins was less effective in resistant clones than in progenitors, targeting PI3K/Akt/mTOR might be a more efficient option against PTX-resistant cancer than apoptotic induction." (PMID 29374144, 2018). "The mammalian target of rapamycin (mTOR) /ribosomal protein S6 kinase (p70S6K) pathway and p38/Jun-amino-terminal kinase (JNK) pathway are proposed to be highly associated with the anti-cancerous activities of TSN in various cancer cell lines." (PMID 30213025, 2018). "In addition to the central role of the PI3K/AKT/mTOR signaling network dysregulation in cancer cells, recent evidence highlights that targeting this pathway can also impact on the host immunity." (PMID 30126252, 2018). "The risk of de novo cancer (hazards ratio (HR) 0.80, 95% CI [0.60–1.09], p = 0.16) and risk of death (HR 1.14, 95% CI [0.82–1.60], p = 0.43) was not different between mTOR inhibitor user and non-user groups." (PMID 30473931, 2018). "Indeed, drugs which inhibit mTOR, named rapalogs, have proven clinical benefits in cancer patients and were approved for the treatment of different advanced neoplasias." (PMID 30061533, 2018). "In this study, we found that treatment with mTOR inhibitors did not reduce the risk of de novo cancer development in kidney transplantation patients, a result that contradicts that of previous studies." (PMID 30473931, 2018).